CTLA4 (cytotoxic T-lymphocyte associated protein 4)
Diseases named in the same sentence as CTLA4 in open-access papers (continued):
Sharing a sentence is not in itself a finding about the gene and the disease.
tumor (continued). "Blocking antibodies to CTLA-4 cause T cell infiltration into tumors in mice and patients, CTLA-4 blockade synergizes with radiation therapy in murine models, and the combination has been associated with a case of tumor regression in patients." (PMID 23653658, 2013). "In our analysis we observed statistically significant association among the increased CTLA-4 mRNA expression and tumor size." (PMID 23936819, 2013). "Statistical analysis revealed significant association between the increased gene expression level and tumor staging according to TNM staging: in T2 tumors CTLA-4 expression was significantly higher than in T3 + T4 group (P = 0.007, Newman-Keuls test)." (PMID 23936819, 2013). "The mechanisms underlying enhanced tumor rejection after CTLA-4 blockade have been evidenced, in part from animal studies using microbe infection." (PMID 23533456, 2013). "There were also significantly fewer activated T cells and more CTLA-4+ conventional T cells susceptible to immune regulation in the tumor-associated mucosa." (PMID 22319577, 2012). "Anti-CTLA-4 aptamer promotes T-cell expansion and anti-tumor immunity in mice, as well as increasing the susceptibility of weakly immunogenic tumors to chemotherapy." (PMID 23130020, 2012). "Tumor-associated Treg had a high expression of CTLA-4, and some appeared to be antigen experienced effector/memory cells based on their expression of αEβ7 (CD103)." (PMID 22319577, 2012). "Several reports in melanoma patients have demonstrated abscopal regression following treatment with local RT and anti-CTLA-4 (ipilimumab) that was associated with elevated immunity to tumor-associated antigens." (PMID 23087904, 2012). "In a pilot study on 15 patients treated with anti-CTLA-4 Tremelimumab, clinical response was also associated with increased tumor infiltration by CD8+ TIL and a variable association with CD4+ TIL." (PMID 23284620, 2012). "Like CTLA-4, PD-1 can attenuate effector T-cell proliferation and effector function, causing anti-tumor immune responses to fail." (PMID 21559358, 2011). "Because of inhibitory effects on immune response, low B7-1 expression on murine colon carcinoma cell lines has been implicated as a possible immune-escape mechanism for tumor cells, presumably through binding of the inhibitory T-cell receptor CTLA-4." (PMID 21127709, 2010). "Subsequently, scientists discovered key immune checkpoint molecules involved in tumor immune evasion, including cytotoxic T‐lymphocyte‐associated antigen 4 (CTLA‐4) and programmed cell death protein 1 (PD‐1), which led to the development of a series of immune checkpoint inhibitors (ICIs)." (PMID 41574027, 2026). "ICIs are monoclonal antibodies that block down-regulators of adaptive immunity, including cytotoxic T lymphocyte-associated protein 4 (CTLA-4), programmed cell death protein 1 (PD-1), and its ligand (PD-L1), unleashing effector T-cell activity and reinstating anti-tumor activity." (PMID 40741581, 2025). "Drugs targeting immune checkpoints, such as Cytotoxic T-Lymphocyte-Associated Protein 4 (CTLA-4), Programmed Cell Death Protein 1 (PD-1), and Programmed Death-Ligand 1 (PD-L1), can enhance the anti-tumor immune response and enable T cells to more effectively eradicate cancer cells." (PMID 40948771, 2025). "In CLL, exhausted T cells exhibit increased expression of inhibitory receptors such as PD-1 (programmed cell death protein 1) and CTLA-4 (cytotoxic T- lymphocyte-associated protein 4), which dampen their effector functions and contribute to immune evasion by tumor cells." (PMID 39930533, 2025). "ICIs primarily work by inhibiting cytotoxic inhibitory signaling pathways that tumor cells exploit to evade immune detection, such as cytotoxic T-lymphocyte-associated protein 4 (CTLA-4), programmed cell death protein 1 (PD-1) on T cells, and programmed cell death ligand 1 (PD-L1) on tumor cells." (PMID 41287707, 2025).
tumor (continued). "These therapies function by stimulating the host immune response, targeting inhibitory pathways such as programmed death-ligand 1 (PD-L1), programmed death-1 (PD-1), and cytotoxic T-lymphocyte-associated protein 4 (CTLA-4), which are exploited by tumor cells to evade immune surveillance." (PMID 40697375, 2025). "In microglia–T cell interactions, CX3CR1-dependent CXCL10 expression mediates microglial recruitment to the tumor site, where they implement T cell suppression through multiple immune checkpoints, including PD-1, cytotoxic T lymphocyte-associated protein 4 (CTLA-4), and forkhead box P3 (Foxp3)." (PMID 40948940, 2025). "Humanized or fully human monoclonal antibodies specially designed to break cancer immune tolerance by restoring T cell recognition against tumor cells, ICIs dampen the cytotoxic T-lymphocyte-associated antigen 4 (CTLA-4) and the programmed cell death 1 (PD-1)/ligand (PD-L1) pathways." (PMID 40558275, 2025). "Furthermore, S100A2+ tumor subset supported the homeostasis of FOXP3+ regulatory T cells with CD86-CD28/CTLA-4 (cytotoxic T lymphocyte-associated protein 4) interaction." (PMID 40092486, 2025). "ICIs function by alleviating inhibitory barriers on T cells, such as programmed cell death 1 (PD-1) and cytotoxic T lymphocyte-associated protein 4 (CTLA-4), or by mitigating coinhibitory signals on tumor cells and antigen-presenting cells, like programmed cell death ligand-1 (PD-L1)." (PMID 39866435, 2025). "Here, we report that Fc-optimized anti-cytotoxic T lymphocyte antigen 4 (CTLA-4) antibodies are potent remodelers of tumor vasculature that increase tumor-associated high endothelial venules (TA-HEVs), specialized blood vessels supporting lymphocyte entry into tumors." (PMID 40460830, 2025). "These monoclonal antibodies work by disrupting the immunosuppressive signals generated by cancer cells through targeted blockade of cytotoxic T-lymphocyte-associated antigen 4 (CTLA-4) and programmed death protein 1 (PD-1) on T cells, or its ligand on tumour cells, programmed death ligand 1 (PD-L1)." (PMID 40673289, 2025). "Bioinformatic analyses revealed that through METTL3 and IGF2BP2, circQSOX1 was upregulated and sponged with miR-326 and miR-330-5p to promote PGAM1 expression, which further activated glycolysis and cytotoxic T-lymphocyte-associated antigen-4 (CTLA-4) expression, contributing to tumor immune escape." (PMID 41373022, 2025). "Interestingly, both RON loss or inhibition in the tumor cooperated with the T-cell checkpoint inhibitor CTLA-4 to reduce tumor growth with responses associated with increased intratumoral lymphocytes and higher T-cell activation markers." (PMID 40282397, 2025). "Immune checkpoint inhibitor (ICI) therapeutics is a growing area of cancer immunotherapy that serves to induce anti-tumor immune responses via a blockade of immune checkpoint proteins, namely, programmed cell death protein 1 (PD-1) and cytotoxic T-lymphocyte associated protein 4 (CTLA-4)." (PMID 40563660, 2025). "ICIs act as antibodies against immune checkpoints such as cytotoxic T-lymphocyte-associated protein 4 (CTLA-4) or programmed cell death ligand 1 (PD-L1) and programmed cell death protein 1 (PD-1), thereby restoring the ability of immune cells to kill tumor cells." (PMID 40406096, 2025). "Immune checkpoint inhibitors (ICIs), such as monoclonal antibodies targeting Programmed Cell Death Protein 1 (PD-1), Programmed Death-Ligand 1 (PD-L1) and Cytotoxic T-Lymphocyte-Associated Protein 4 (CTLA-4), have revolutionized cancer therapy by reactivating suppressed anti-tumor immune responses." (PMID 41305010, 2025). "Interestingly, despite the stimulatory effect of CD80 binding to CD28, it was found that deactivating CD80 reduces tumour growth and increases susceptibility to anti-CTLA-4 antibody treatment." (PMID 40725864, 2025).
tumor (continued). "Butyrate, in particular, enhances the expression of CTLA-4 (cytotoxic T-lymphocyte-associated protein 4) on Tregs, which suppresses immune responses and promotes an immunosuppressive environment that may affect tumor growth and immune tolerance." (PMID 40243570, 2025). "In terms of CAR-T cell function optimization, CRISPR technology significantly enhances anti-tumor activity and reduces the risk of allogeneic rejection by targeting and knocking down immune checkpoint genes (e.g., PD-1, CTLA-4) and endogenous T cell receptors (TRAC/TRBC)." (PMID 40697666, 2025). "Immune checkpoints hamper anti-tumor immune responses, and the use of antibodies to block cytotoxic T-lymphocyte-associated protein 4 (CTLA-4) or programmed death 1 (PD-1) pathways – achieving immune checkpoint blockade (ICB) – can enhance anti-tumor immune responses." (PMID 40771747, 2025). "By interrupting the binding between receptors and tumor-derived ligands, such as cytotoxic T lymphocyte-associated protein 4 (CTLA-4), programmed cell-death protein-1 (PD-1) and programmed death-ligand-1 (PD-L1), these mAbs have revolutionized the treatment of several malignancies." (PMID 41153826, 2025). "ICIs primarily target negative immune checkpoint molecules, including cytotoxic T lymphocyte-associated antigen 4 (CTLA-4), programmed death 1 (PD-1), and programmed death-ligand 1 (PD-L1), which are involved in strengthening the immune response and postponing tumor advancement." (PMID 41024179, 2025). "Key strategies include immune checkpoint inhibitors, which block inhibitory receptors like programmed cell death protein 1 and cytotoxic T-lymphocyte-associated protein 4, and adoptive cell therapies, which involve the transfer of tumor-specific T cells or NK cells into patients." (PMID 41181425, 2025). "Our findings suggest that CTLA-4 expression in HNSCC is associated with tumor progression to high-grade neoplasia and may serve as a marker of tumor biological behavior." (PMID 40861696, 2025). "Neoadjuvant anti-PD-L1 (durvalumab) plus anti-CTLA-4 (tremelimumab) treatment of cisplatin-ineligible patients with urothelial cancer (UC) had higher density TLS in pretreatment tumor specimens of responders (R) associated with longer recurrence-free survival (RFS) and OS." (PMID 40475770, 2025). "ICIs can enhance the activity of immune cells and promote the immune system’s attack on tumor cells by inhibiting the immune checkpoint molecules such as cytotoxic T-lymphocyte-associated protein 4 (CTLA-4), programmed death 1 (PD-1), and programmed cell death ligand 1 (PD-L1)." (PMID 41142624, 2025). "Ipilimumab was created clinically following preliminary preclinical research that confirmed proof of concept showing antibodies against CTLA-4 might cause tumor regression." (PMID 40296914, 2025). "It is worth noting that factors like tumor mutation burden, heterogeneity of PD-1 and CTLA-4 expression in host and malignant cells, and other patient-specific characteristics may influence a patient’s risk of experiencing neurologic irAEs." (PMID 40351833, 2025). "Preclinical models demonstrated complete tumor regression and sustained immunological memory in 40–60 % of anti-CTLA-4-treated mice, effects mechanistically linked to enhanced CD8+ effector T cell/Treg ratios (4.8 vs. 1.6 in controls) through FoxP3+ cell depletion." (PMID 41209702, 2025). "Immune checkpoints like PD-1, PD-L1, and cytotoxic T lymphocyte-associated antigen 4 (CTLA-4) are a group of regulatory molecules that limit the damage caused by immune responses to normal tissues, and are also used by tumor cells to escape immune surveillance." (PMID 41472727, 2025). "This dual role of immunomodulation and intrinsic tumor suppression makes LAG3 distinct from PD‐1/CTLA‐4 and may explain the association of anti‐PD‐1 resistance with LAG3/FGL1 co‐expression." (PMID 41025546, 2025).
tumor (continued). "Ipilimumab is a fully human, monoclonal antibody that blocks the cytotoxic T lymphocyte-associated antigen 4 (CTLA-4) signalling, which induces an unrestrained T-cell activation and proliferation and amplifies T-cell-mediated immunity (anti-tumour immune response)." (PMID 40507314, 2025). "Notably, gene expression analysis showed that SCC tumours exhibited higher expression of Cytotoxic T-Lymphocyte Associated protein 4 (CTLA-4)." (PMID 40639721, 2025). "The immune environment of ccRCC is distinct, marked by a high presence of immune cells like CD8+ T cells, regulatory T cells (Tregs), and tumor-associated macrophages (TAMs), alongside increased expression of immune checkpoint molecules such as CTLA4, PD-1, and LAG3." (PMID 40243888, 2025). "We analyzed the association between sTIM-3 and overall survival (OS), tumor response, and common clinical and biological factors in two mccRCC cohorts treated with anti-PD-1 (nivolumab, n = 27), anti-PD-1 or anti-PD-1 + anti-CTLA-4 (nivolumab + ipilimumab – N + I, n = 124)." (PMID 39953623, 2025). "Furthermore, tumor-intrinsic YTHDF1 deficiency demonstrated synergistic effects with anti-CTLA-4 or anti-PD-L1 antibodies, leading to reduced tumor volume and extended overall survival in mice bearing B16/F10 cells." (PMID 39987091, 2025). "Moreover, overexpression of IKZF1 has been associated with increased recruitment of anti-tumor immune cell infiltrates and sensitivity to anti-PD-1 and anti-CTLA4 therapy." (PMID 40428397, 2025). "The purpose of immune checkpoint inhibitors is to increase T lymphocytes’ immune response against tumor cells by blocking immunological checkpoint molecules like programmed cell death protein 1 (PD-1), cytotoxic T-lymphocyte-associated protein 4 (CTLA-4), and programmed death ligand 1 (PD-L1)." (PMID 39728071, 2024). "In addition, immune checkpoints like CTLA-4 (cytotoxic T-lymphocyte-associated protein 4) and PD-1 (programmed cell death protein 1) are critical for immune response regulation, and their upregulation on tumor cells can lead to adaptive immune resistance." (PMID 39188717, 2024). "Previous evidence suggests that anti-epidermal growth factor receptor (EGFR) therapies may enhance tumor response and trigger an immunogenic apoptosis cascade that is usually associated with increased expression of CTLA4 and PDL1." (PMID 39080202, 2024). "However, their cytotoxic function is often suppressed by tumor-induced immune checkpoints, such as programmed death-1 (PD-1) and cytotoxic T-lymphocyte-associated protein 4 (CTLA-4)." (PMID 39351232, 2024). "Interestingly, Bacteroides fragilis has been previously associated with favorable anti-tumor immune responses following treatment of patients with anti-CTLA-4 whereas gut-resident Prevotella species had the opposite effect." (PMID 38662827, 2024). "However, the functional consequences of this mutation on CTLA-4 activity and its potential role in tumor survival remain to be fully understood." (PMID 38542966, 2024). "An inhibition of these molecules, exploiting immune checkpoint inhibitors (CPIs) such as the PD-1 inhibitor nivolumab and the CTLA-4 inhibitor ipilimumab, causes an enhancement of tumor directed CD 8+ T cells, which can result in durable remission of different tumor types." (PMID 38915369, 2024). "CpG-PBNP-PTT with anti-CTLA-4 in vivo caused complete tumor regression in mice." (PMID 39062971, 2024). "Immune checkpoint inhibitors counter the endogenous inactivation or exhaustion of anti-tumor adaptive immunity by cytotoxic CD8+ T cells via blocking the programmed cell death (PD-1) or cytotoxic T lymphocyte-associated antigen-4 (CTLA4) pathways in various tumor types." (PMID 38330013, 2024). "For instance, studies have shown that targeting both CTLA-4 and PD-1 expands cytotoxic T cells and transforms tumor-associated monocytes and macrophages to a pro-inflammatory (M1) phenotype through increased IFN-γ secretion, producing an inflammatory tumor microenvironment (TME)." (PMID 38956700, 2024).
tumor (continued). "Immunotherapy has focused on augmenting cell-mediated immunity with a biological anti-tumor cell response, and involves the use of antibodies against cytotoxic T lymphocyte-associated antigen 4 (CTLA-4) and against the programmed death-1 (PD-1) and its ligands such as PD-L1 and PD-L2." (PMID 39272828, 2024). "Since in the cancer setting, tumor cells may use cytotoxic T-lymphocyte-associated protein 4 (CTLA-4) to evade the immune system." (PMID 39143529, 2024). "A previous study showed that immune inhibitory anti-CTLA4 (Ipilimumab) treatment could increase IFNγ production by T cells—and IFNγ-related gene deficiency in tumor cells induced resistance to anti-CTLA4 immune checkpoint therapy." (PMID 38167862, 2024). "Immune checkpoint blockade (ICB) represents a novel groundbreaking tumor immunotherapy that targets two key immune checkpoint pathways programmed cell death protein 1/programmed death ligand 1 (PD-1/PD-L1) and cytotoxic T lymphocyte-associated protein 4/B7 (CTLA-4/B7)." (PMID 38745666, 2024). "Furthermore, RCT001, an optimized CXCR2 inhibitor, enhances the efficacy of anti-CTLA4 + anti-PD1 therapies by inhibiting tumor-associated M2 macrophages and tumor-associated neutrophils." (PMID 39014460, 2024). "Thus, by blocking the CTLA-4 pathway, T-cells that were previously inactive can become activated and effectively target the tumor cells, causing a more powerful immune response against the cancer." (PMID 38410760, 2024). "Therefore, tumor patients with a deficient MMR or MSI-H are likely to benefit from anti-PD-1/PD-L1/CTLA-4 treatments." (PMID 38280988, 2024). "CTLA-4 is a key protein associated with tumor immune evasion." (PMID 38983866, 2024). "Also, T cells in the tumor microenvironment (TME) upregulate the expression of checkpoint molecules such as cytotoxic T lymphocyte-associated protein 4 (CTLA-4)." (PMID 38191571, 2024). "Among cancer immunotherapies, the most common are interleukin, tumor vaccines and ICls such as death protein-1 (PD-1) and cytotoxic T-lymphocyte-associated protein 4 (CTLA-4) inhibitors as well as Chimeric Antigen Receptor T-Cell Immunotherapy (CAR-T) cell therapy." (PMID 39737395, 2024). "Anti-PD-1, anti-PDL1, and anti-CTLA4 (Cytotoxic T-Lymphocyte Associated Protein 4) are monoclonal antibodies against these ligands and receptors and proved to be effective in inducing tumor regression in different tumors, especially when combined with other traditional anti-cancer drugs." (PMID 38539471, 2024). "In MTC, it has been suggested that tumour-associated CTLA-4 expression is exclusive to sporadic cases and may contribute to the stage-adjusted worse prognosis seen when comparing sporadic and hereditary disease." (PMID 39001359, 2024). "Immune checkpoint therapy can stimulate an anti-tumor response by restoring T cell function through complex interactions among immune checkpoint molecules, such as PD-1, its ligand (PD-L1), and cytotoxic T lymphocyte-associated protein (CTLA-4)." (PMID 38542078, 2024). "However, specific mechanisms underlying CTLA-4 expression in B-cells within the tumour microenvironment are uncharacterised." (PMID 38893123, 2024). "Tumor cells exploit PD-1 and CTLA-4 to cause tumor tolerance and T-cell exhaustion." (PMID 38893220, 2024). "Cytotoxic T lymphocyte-associated antigen 4 (CTLA-4) was the first protein to be targeted to manipulate the immune system against cancer, as its blockade enhances the T-cell immune response and inhibits tumour growth." (PMID 39215193, 2024). "Additionally, the combination of anti-cytotoxic T-lymphocyte-associated protein 4 (CTLA4) or anti-lymphocyte activation gene 3 (LAG3) with anti-PD1 antibodies has further increased tumor response rates through unleashing potent immune effector mechanisms." (PMID 38473216, 2024).